MMP1 (matrix metallopeptidase 1)
Diseases named in the same sentence as MMP1 in open-access papers (continued):
Sharing a sentence is not in itself a finding about the gene and the disease.
keloid (21 papers, 2012 to 2025). An irregularly shaped, elevated mark on the skin caused by deposits of excessive amounts of collagen during wound healing. "In this study, although not statistically significant, IL-1β induced higher amounts of matrix metalloproteinase-1 (MMP-1) production by cultured skin fibroblasts derived from normal controls than those produced by keloid-derived skin fibroblasts." (PMID 39799030, 2025). "This elevation mirrors that found in keloid fibroblasts, which suppress matrix metalloproteinase-1 (MMP-1), the enzyme responsible for breaking down collagen type I, thereby reducing ECM turnover." (PMID 39114830, 2024). "We identified four subpopulations of endothelial cells in keloid and normal scar tissue by scRNA-seq data: MMP1+ Endo0, FOS + JUN + Endo1, IL6+CSF3+ Endo2, CXCL12 Endo3." (PMID 36082167, 2022). "Gallic acid inhibited keloid fibroblast proliferation, migration, and invasion as well as downregulated MMP-1 and MMP-3 and upregulated the tissue inhibitors of MMP-1, effects associated with the suppression of the protein kinase B signaling pathway." (PMID 36364354, 2022). "The results demonstrated that keloid dermal fibroblasts exhibited significantly increased expression of MMP-1, MMP-2, and MMP-3 relative to normal or hypertrophic dermal fibroblasts." (PMID 33672186, 2021). "Increasing expression of decorin by adenovirus in keloid fibroblasts significantly decreased collagen synthesis and stimulated the transcription level of MMP-1 and MMP-3." (PMID 34768882, 2021). "Results of a diminished production of PGE2 and MMP-1 by IL-1-stimulated keloid-derived fibroblasts may provide more information about factors contributing to keloid formation." (PMID 39799030, 2025). "However, in keloid fibroblasts, MMP-1, which cleaves collagen types I and III, is decreased, while MMP-3, a stromelysin, is increased." (PMID 38892032, 2024). "To further explore the impact of EP on the expression of ECM-degrading enzymes in keloids, we assessed the mRNA expression levels of metalloproteinase I (MMP1), metalloproteinase III (MMP3), and tissue inhibitor of metalloproteinases I (TIMP1) in both TGF-β1-treated HDFs and KFs." (PMID 38892032, 2024). "Furthermore, we found that differentiation of IL6+CSF3+ activated endothelial cells to MMP1+ endothelial cells activated by the NFΚB signaling pathway is a major feature of keloid vascular lesions." (PMID 36082167, 2022). "As previously reported, EGF treatment of all dermal fibroblasts significantly induced an increase in MMP-1 expression, and both normal and keloid dermal fibroblasts showed increased MMP-9 expression, whereas hypertrophic dermal fibroblasts showed a significant decrease in MMP-9 expression." (PMID 33672186, 2021). "Conversely, the down-regulation of MMP1 may lead to keloid and hypertrophic scarring." (PMID 32900003, 2020). "EP treatment also increased MMP1 expression, improved the MMP-to-TIMP ratio, and suppressed ECM formation, suggesting potential therapeutic benefits in keloid treatment." (PMID 38892032, 2024). "Consistently, western blot analysis showed that up-regulation of ATF3 significantly promoted levels of MMP1/2/9/13, whereas siRNA ATF3 led to an inhibition of MMP1/2/9/13 in keloid fibroblast cells." (PMID 33315500, 2021). "On the other hand, MMP-1, MMP-2, and TIMP1 were significantly upregulated in keloid fibroblasts by CM." (PMID 35083233, 2021). "The majority of literatures reported the upregulation of MMP1 and MMP3, because they greatly contributed to the invasion of KFs, allowing the keloids to extend beyond the wound boundary." (PMID 27339758, 2016). "Given that PGE2 enhances MMP-1 expression, the reduced PGE2 levels in keloids may be responsible for the decreased MMP-1 production by keloids and their subsequent accumulation of extracellular matrix (ECM)." (PMID 23634948, 2013). "MMP1 and MMP3 were expressed at lower levels in keloid ESS compared with normal ESS and were not significantly increased after wounding." (PMID 22536458, 2012).
periodontal disease (21 papers, 2012 to 2025). "A number of candidate gene studies showed that IL1A, IL1B, IL4, IL6, IL10, TNFA, FcγR, VDR, TLR2, TLR4, and MMP1 were the main genes associated with periodontal disease." (PMID 36294882, 2022). "Additionally, it has been demonstrated that P. gingivalis DPP-4 increases the activity of host-derived matrix metalloproteinases (MMP)-1 (collagenase) and -2 (gelatinase), which are hypothesized to be implicated in the breakdown of connective tissue in periodontal disease." (PMID 40429343, 2025). "The regimen reduced pathogenic bacteria, IL-1β, MMP1, and MMP-9, paralleling clinical reductions in periodontal disease." (PMID 41303313, 2025). "Collectively, the data support a reduction in host mediators (e.g., TLR-ATP, IL-1β, MMP-1, and MMP-9) with regimen treatment that are implicated in inflammation and periodontal disease destruction." (PMID 41303313, 2025). "Fibrous collagenases such as MMP1 and MMP13 have been associated with diabetic complications and periodontal disease." (PMID 39456763, 2024). "High levels of MMPs, such as MMP-1, -2, -8, -9, and -13, are related to the severity and tissue destruction of periodontal disease." (PMID 37373533, 2023). "For example, MMP-1 plays a role in degrading collagen in periodontal tissues during the progression of periodontal disease." (PMID 36246974, 2022). "MMP-1 mainly degrades the collagen present in periodontal tissues during periodontal disease progression." (PMID 34504537, 2021). "In addition, GLE restored ALP and OCN, specific markers of periodontal tissue production and osteoblast differentiation lost by PG-LPS, and conversely inhibited the production of MMP-1, known as the main tissue-destroying protease in periodontal disease." (PMID 40733170, 2025). "Additionally, the MMP1 enzyme is an enzyme that destroys the connective tissue of the gums that occurs in periodontal disease and is said to be regulated by tissue inhibitor of metalloproteinase (TIMP)." (PMID 38202632, 2023). "This suggests that MKE might have potential to treat periodontal disease by inhibiting collagenases (MMP-1, -8, -13), gelatinase (MMP-9), and stromelysin (MMP-3)." (PMID 36661522, 2023). "In addition, MMP1 levels have been found to be decreased after periodontal treatment, highlighting the pathophysiological role of this collagenase in periodontal disease conditions." (PMID 33513808, 2021). "Matrix metalloproteinase (MMP)-1 and MMP-9 which played an important role in both diseases are upregulated in OLP patients with periodontal diseases." (PMID 36360666, 2022). "Among these MMPs, MMP-1 (collagenase I) and MMP-3 (stromelysin) play major roles in periodontal disease development." (PMID 36246974, 2022). "The results of the present study confirm that MF suppresses MMP-1, MMP-2, MMP-8 and IL-8 in LPS-stimulated HGFs suggesting an anti-inflammatory effect of MF and potential adjunct therapeutic role in the treatment of periodontal diseases." (PMID 37189090, 2023). "Especially, MMP-1 and MMP-3 are important in periodontal diseases." (PMID 34504537, 2021). "MMP-1 (collagenase I) and MMP-3 (stromelysin) play important roles in periodontal diseases." (PMID 34504537, 2021). "Salivary biochemical markers, which are characteristic for periodontal disease, include enzymes (MMP-1 (matrix metalloproteinase-1), MMP-8 (matrix metalloproteinase-8), MMP-9 (matrix metalloproteinase-9), immunoglobulins, and a group of proteins (albumin, fibronectin)." (PMID 32598403, 2020). "Therefore, inhibition of MMP-1 and MMP-3 production leads to the treatment of periodontal disease." (PMID 34066937, 2021). "Interestingly, our results show original evidence that F. alocis may contribute to periodontal destruction through MMP-1 and to periodontal inflammation through COX2, demonstrating its role in two different stages of the periodontal disease process." (PMID 32089643, 2020).
periodontal disease (continued). "However, other authors did not found differences in MMP-1 and MMP-8 expression in periodontal tissue and gingival crevicular fluid of diabetic and nondiabetic patients, both with periodontal disease." (PMID 22611374, 2012).
glaucoma (20 papers, 2009 to 2025). Increased pressure in the eyeball due to obstruction of the outflow of aqueous humor. "Meta-analyses revealed an increased risk of glaucoma associated with the MMP1 rs1799750 polymorphism and a possible protective role of the MMP9 rs17576 G>A polymorphism against the development of glaucoma in the Caucasian population." (PMID 39769228, 2024). "Its level has also been shown to be elevated in glaucoma and its overexpression increases the collagen expression level while, its induction by glucocorticoids caused the up-regulation of important glaucoma-related proteins including fibronectin, myocilin and MMP1." (PMID 28264047, 2017). "Viral vector-mediated delivery of MMP-1 has been found to reverse elevated IOP in the trabecular meshwork of sheep with steroid-induced glaucoma." (PMID 35457074, 2022). "Another MMP that seems to play a significant role in the outflow of aqueous humor and glaucoma is MMP-1." (PMID 35457074, 2022). "The MMP-1 in the sclera is likely responsible for the remodeling of scleral ECM-enhancing uveoscleral turnover; this would account for the observed upregulation of MMP-1 expression in glaucoma." (PMID 35457074, 2022). "Relative to the organization and remodeling of the ECM in the TM and in glaucoma, we observed a large decrease in MMP1 expression in both cell lines (CAβ3 FC = −6.35, WTβ3 FC = −3.59)." (PMID 34440692, 2021). "Presently, TDRD7, CYP1B1, GJA1, IL1B, MMP1, and MMP3 have been considered as a causative gene for glaucoma." (PMID 33299458, 2020). "In the optic nerve heads of both human glaucomatous eyes and monkey eyes with experimental glaucoma increased expression of MMP1 has been reported." (PMID 20808730, 2010). "MMP1, MMP2, and MMP9 have previously been implicated in the pathogenesis of primary open angle glaucoma (POAG) and open angle glaucoma secondary to exfoliation syndrome (XFG), respectively." (PMID 20808730, 2010). "TIMPs were increased in the plasma of untreated children with JIA, have been associated with levels of matrix metalloproteinase (MMP)-1, MMP-3, and TIMP1 in paired serum and synovial fluid also in those with JIA, and were found in AqH of patients with glaucoma." (PMID 30327966, 2018). "In studies focusing on prostaglandin analogue-treated glaucoma patients, IL1B, IL6, and matrix metallopeptidases 1, 3, and 9 (MMP1, MMP3, and MMP9) were seen to be increased, while TIMP metallopeptidase inhibitors 1 and 2 (TIMP1 and TIMP2) were decreased." (PMID 35897711, 2022). "Strikingly, the staining intensity of MMP1 and MMP3 in the outflow pathway of exfoliating glaucoma, a type of secondary glaucoma characterized by the extracellular accumulation of non-internalized exfoliating material in the angle chamber, was significantly diminished compared to POAG." (PMID 22529935, 2012). "The distribution of genotypes and alleles in MMP1 and MMP3 polymorphisms was not significantly different between cases with exfoliation syndrome, with or without glaucoma, and controls." (PMID 20038976, 2009).
pulmonary TB (20 papers, 2009 to 2025). "Genetic polymorphisms that result in greater MMP-1 secretion in pulmonary TB have been identified as a risk factor for developing fibrosis following TB." (PMID 34093524, 2021). "Hypoxia increases gene expression and secretion of MMP-1, a key collagenase that causes tissue destruction and immunopathology in pulmonary TB." (PMID 27245780, 2016). "Infection with S. stercoralis in the context of active pulmonary TB was associated with significantly lower levels of MMP-1 (GM of 5.3 ng/ml in ATB vs. 3.9 ng/ml in ATB+Ss) and MMP-9 (GM of 646.4 ng/ml in ATB vs. 331.2 ng/ml in ATB+Ss) - when compared to Ss-uninfected individuals with active TB." (PMID 25375117, 2014). "The Matrix Metalloproteinase (MMP)-1 gene, which encodes a potent collagenase, is an excellent candidate gene for influencing the expression of pulmonary TB since inflammation-mediated tissue damage may contribute to the spread of M. tuberculosis infection." (PMID 20111728, 2010). "The results were supported by a study wherein the circulating levels of MMP-1 were found to be elevated in active pulmonary TB patients as compared to individuals with LTBI." (PMID 36776550, 2022). "In pulmonary TB MMP-1, interstitial collagenase, is the main effector of lung degradation and cavity formation." (PMID 34093524, 2021). "After completion of anti TB treatment, matrix-degrading phenotype solves quickly in patients with fully drug-sensitive pulmonary TB and the levels of MMP-1, − 3 and − 8 concentrations in sputum decline markedly in the first 2 weeks of anti-TB treatment." (PMID 30045688, 2018). "Our group has demonstrated that in pulmonary TB, MMP-1 is the key in the immunopathology of disease and is expressed within TB granulomas and in adjacent airway epithelial cells." (PMID 29988449, 2018). "We previously reported that that MMP-1, − 7 and − 8 plasma levels were significantly elevated in children with pulmonary TB compared to healthy controls." (PMID 30045688, 2018). "For example, HMOX1 downregulated the expression and secretion of MMP-1 in chondrocytes or plasma of patients with pulmonary tuberculosis." (PMID 27829220, 2016). "MMPs-1, -2, -3 and-8 were increased in the induced sputum of patients with pulmonary TB and MMP-1 correlated with extent of radiological infiltration." (PMID 25635689, 2015). "Univariate analysis of MCP-1 and MMP-1 genotypes and progression to pulmonary tuberculosis in Mexicans." (PMID 20111728, 2010). "Univariate analysis of MCP-1 and MMP-1 genotypes and progression to pulmonary tuberculosis in Peruvians." (PMID 20111728, 2010). "Similarly, studies in adults with pulmonary TB have shown increased circulating levels of MMP1, 2, 3, 7, 10, 12, and 13 compared to healthy controls." (PMID 40558582, 2025). "In particular, a recent report revealed that MMP-1(-1607G), a member of MMP-9, and its polymorphism could act as a risk factor for fibrosis after pulmonary tuberculosis in Taiwan." (PMID 38235425, 2023). "In addition, we have shown that MMP-1, − 7 and − 8 plasma levels were significantly elevated in children with pulmonary TB." (PMID 30045688, 2018). "The contribution of the -1607 MMP-1 genotype 2G/2G to the expression of active pulmonary TB might also be population-specific since the frequency of the allele 2G in Caucasians (0.433) and non-Caucasian Africans (0.375) is lower than in Mexicans (0.73) and Peruvians (0.71)." (PMID 20111728, 2010). "Previous research in the pediatric population has indicated elevated levels of MMP1, 7, 8, and TIMP 1, 3 in children with pulmonary TB compared to those with extrapulmonary TB and healthy controls." (PMID 40558582, 2025). "Epigenetic regulation of MMP-1 and MMP-3 (a physiological MMP-1 activator) modulates the immune response against Mycobacterium tuberculosis (Mtb) in pulmonary tuberculosis." (PMID 33920915, 2021).
pulmonary TB (continued). "When only the individuals with pulmonary TB were compared to those with ORD, significant differences were observed for SAA, CRP, VEGFR3, RANTES, Pentraxin3, Ferritin, CCL18, MPO, GDF-15, MMP-1, PDGF-BB, Procalcitonin, MDC, Myoglobin, and VCAM-1." (PMID 33732236, 2021). "The collagenases, MMP-1 and MMP-8, were elevated in plasma of patients with pulmonary TB relative to healthy controls, and MMP-7 (matrilysin) and MMP-9 (gelatinase B) were also increased." (PMID 25635689, 2015). "In summary, plasma MMP-1 and MMP-8 are elevated in active pulmonary TB, implicating excessive collagenase activity in TB immunopathology." (PMID 25635689, 2015). "In addition, studies have found that the content of MMP-1, MMP-9, and other matrix metalloproteinases in bronchoalveolar lavage fluid of pulmonary tuberculosis patients is significantly increased." (PMID 35388750, 2023). "MMP-1 and its activator MMP-3 were found to be related to the TB disease severity and treatment efficacy, while MMP-13 together with TIMP-2 were proved to be potential indicators of extra-pulmonary TB in adults." (PMID 33923293, 2021). "In this study, serum levels of interferon gamma (IFN-γ), matrix metalloproteinases 1 and 9 (MMP-1 and MMP-9, respectively), and periostin were compared between 40 pulmonary tuberculosis (PTB) and 28 non-tuberculous pneumonia (non-PTB) patients." (PMID 31917802, 2020).